FASN (fatty acid synthase)
Diseases named in the same sentence as FASN in open-access papers (continued):
Sharing a sentence is not in itself a finding about the gene and the disease.
cancer (continued). "Recent evidence showed that FASN plays a crucial role in the carcinogenesis process of various cancers including OvCa." (PMID 30619288, 2018). "In normal adult tissues, FASN expression is very low, while in several types of cancer, such as prostate and breast cancer, it is significantly upregulated." (PMID 29805774, 2018). "Fatty acid synthase (FASN) was reported to be elevated in many cancers, including breast, prostate and other types of cancer." (PMID 30532734, 2018). "FASN is a known oncotarget, whose expression is enhanced in numerous cancers including DLBCL2,4,5,23." (PMID 29483509, 2018). "EGCG derived from green tea, is also an inhibitor of FASN activity and has anti-tumor effects, inducing apoptosis in several cancer cell lines and reducing tumors size." (PMID 29805774, 2018). "A FASN-TGF-β1-FASN regulatory loop is involved in high EMT/metastatic potential in cisplatin-resistant cancer cells." (PMID 30671168, 2018). "Blocking FASN activity triggers apoptosis in cancer cells and inhibits tumor growth in xenograft models, by disrupting lipid membrane synthesis, protein palmitoylation, and signalling of major oncogenic pathways." (PMID 29751678, 2018). "The enzyme fatty acid synthase (FASN) is highly expressed in cancer cells and its ablation inhibits cancer cell growth." (PMID 30123774, 2018). "Overexpression of fatty acid synthase (FASN), a key regulator of the de novo synthesis of fatty acids, has been demonstrated in a variety of cancers and is associated with poor prognosis and increased multidrug resistance." (PMID 29569717, 2018). "FASN and de novo lipogenesis, its cognate pathway, are critical components of tumor cell survival and proliferation for a wide range of cancers." (PMID 29872506, 2018). "Fatty acid synthase (FASN), a key enzyme in lipogenesis, is significantly upregulated in many cancer." (PMID 30211160, 2018). "FASN has been well documented with regard to its role played in cancer and is exploited extensively as anticancer target." (PMID 30186863, 2018). "Whereas chemotherapeutic agents have been developed to target FASN, due to its importance in providing lipid for cell growth in cancer, many of these agents target the ketoacyl-reductase domain, as it is a chemically more favorable target to inhibit." (PMID 29463677, 2018). "Inhibition of FASN decreases proliferation and diminishes metastatic capabilities of cancer cells in multiple tumor models." (PMID 29872506, 2018). "FASN correlates with poor prognosis in various types of cancer and also interferes with drug efficacy." (PMID 30456204, 2018). "According to the Cancer Chemotherapy Center, newly synthesized fatty acids thrive despite containing numerous exogenous lipids, and a number of lipid metabolism enzymes, including fatty acid synthase, contribute to cancer development and transformation." (PMID 30071629, 2018). "On the other hand, upregulation of FASN was also observed in many types of human cancers, which is required for tumor growth and metastasis." (PMID 30425250, 2018). "Numerous studies have shown that many human cancer cells have high activities of FASN, and the cytotoxic effects of FASN have been described both in vitro and in vivo." (PMID 30619288, 2018). "A previous study demonstrated that inhibition of fatty acid synthase activity arrested the cancer cells at G2/M." (PMID 30388870, 2018). "FASN is important in the synthesis of palmitate, precursor of fatty acids, and is found frequently upregulated in many human cancers." (PMID 29449326, 2018). "The master regulator of FA synthesis, SREBP1, regulates FASN expression to activate FA synthesis in cancer cells." (PMID 29996946, 2018). "Given the dynamic nature of FASN regulation, and the complexity in deciphering its downstream mediators, targeting this enzyme with respect to cancer metabolism remains challenging and an area ripe for further investigation." (PMID 29483509, 2018).
cancer (continued). "The over‐expression of fatty acid synthase (FASN) occurs in cancers, leading to the over‐production of endogenous fatty acids." (PMID 29999584, 2018). "In this sense, some metabolic enzymes such as fatty acid synthase (FASN) have been identified as valuable therapeutic targets for cancer treatment." (PMID 29751678, 2018). "FASN is overexpressed in a variety of human carcinomas, including TNBC, and its inhibition with polyphenolic compounds such as EGCG has been demonstrated to be a promising therapeutic strategy, alone and in combination, for TNBC." (PMID 29751678, 2018). "Clinically, FASN is frequently upregulated in a broad variety of cancers and has been reported to have an oncogenic function." (PMID 28775317, 2017). "Fatty acid synthase (FASN) has arisen as a potential target in different types of cancer and even currently a FASN inhibitor is being evaluated in a clinical trial." (PMID 29088795, 2017). "FASN is one of the key enzymes involved in de novo long-chain fatty acid synthesis, which cancer cells rely on in order to meet their markedly increased demands for membrane and energy production and protein synthesis." (PMID 28086232, 2017). "Next, we treated the HepG2 human cancer cell line with C75 and found that FASN expression and the expression levels of liver‐specific genes, including PKLR, PNPLA3, and PCSK9, were significantly decreased after 24 h." (PMID 28827398, 2017). "Blockade of FASN with EGCG has been considered for broad range of cancer types such as prostate, lung, breast, and colorectal cancer, where several phase 2 and phase 3 clinical trials are ongoing." (PMID 29295482, 2017). "The “lipogenic phenotype” of cancer occurs as lipogenic enzymes, including fatty acid synthase (FASN), are upregulated during oncogenesis-mediated metabolic reprogramming." (PMID 28654693, 2017). "Increases in FASN activity and expression are observed early in cancer development and correlate with cancer progression, while high FASN levels correlate with more aggressive malignant phenotypes." (PMID 28421159, 2017). "FASN appears overexpressed in many cancer types including breast and prostate, suggesting that FA synthesis plays a crucial role in cancer development." (PMID 28752333, 2017). "As such, the role of FASN in cancer pathogenesis is of significant interest and there are numerous reports which attest to its utility as a therapeutic target." (PMID 28086232, 2017). "On the other hand, the addition of palmitate fully restored cancer cell viability after the inhibition of FASN." (PMID 28938608, 2017). "The fatty acid synthase (FASN) is crucial to meet the cancer cells increased demands for membrane via de novo long-chain fatty acid synthesis." (PMID 28676692, 2017). "In all, FASN and/or combined with other lipogenic enzyme genes may develop as potential diagnostic markers for definition of tumor molecular subset with high lipogenic levels, and the inhibition of FASN and lipid synthesis would benefit for cancer treatment resistance." (PMID 28399876, 2017). "As determined by cluster analysis, ETV1 and FASN were differential over-expressed in malignant prostate tissue in comparison with benign biopsies, highlighting their possible relevance as future cancer markers." (PMID 28143451, 2017). "We and others have reported that FASN inhibition (alone or in combination) induces apoptosis in several cancer cells and reduces the growth of human xenografts." (PMID 29088795, 2017). "Available evidence suggests that FASN-dependent cancers likely regulate de novo FA biosynthesis to produce lipids for membrane synthesis and energy production (mechanism 4)." (PMID 28962653, 2017). "Co‐expression analysis in these samples revealed that FASN is co‐expressed with a number of genes that play roles in crucial biological processes involved in fat accumulation and cancer cell metabolism." (PMID 28827398, 2017).
cancer (continued). "Nevertheless, supplementation of OA has been found to significantly alleviate growth inhibition by FASN-blockers and partially restores cancer cell survival, whereas supply of the primary enzyme product PA is rather toxic." (PMID 28086243, 2017). "Suppression of FASN results in cell cycle arrest, reduction in cancer cell proliferation, and increase in apoptosis." (PMID 28373964, 2017). "Both phospholipase and fatty acid synthase are essential for tumor progression and have been identified as potential cancer treatment targets." (PMID 29359123, 2017). "FASN plays an important metabolic role in molecular pathways regulating cancer cell proliferation and tumor development." (PMID 27270654, 2016). "FASN is a key enzyme that regulates FA metabolism and plays an important role in the energy balance in cancer cells." (PMID 26934656, 2016). "Further evidence for de novo lipogenesis in tumors came from the observation that fatty acid synthase (FASN) is overexpressed in several cancers, including breast and PCa." (PMID 27384557, 2016). "At the molecular level, mTORC1 is considered to be the major regulator of FASN-mediated fatty acid synthesis during cancer development." (PMID 26857837, 2016). "Accordingly, the oncogenic nature of FASN overexpression confers tumor aggressiveness and poor prognosis in various human cancers." (PMID 27713913, 2016). "Resveratrol was found to suppress cancer cell proliferation by inhibiting the fatty acid synthase signaling pathway." (PMID 27213347, 2016). "FASN has been shown to have a correlation with lipid body formation in cancer cells in many reports." (PMID 27270654, 2016). "In various cancers, aggressive features such as migration, invasion, metastasis, and chemo-resistance, have been shown to be dependent upon FASN." (PMID 27791206, 2016). "In human cancers, oncogenic lipogenesis is prototypically exemplified through increased fatty acid synthase levels, resulting in enhanced de novo fatty acid synthesis and poor prognosis." (PMID 27366945, 2016). "FASN is a key lipogenic enzyme catalyzing the terminal steps in the de novo biogenesis of fatty acids and plays important role in cancer biology." (PMID 27579768, 2016). "Upregulation of FASN gene expression is an early event in cancer development that is more pronounced in advanced tumors." (PMID 27270654, 2016). "De novo lipogenesis in mammalian cells depends on mitochondrial citrate production and fatty acid synthase amplification has been reported in cancer." (PMID 26754490, 2016). "It has been suggested that overexpression of fatty acid synthase plays an important role in the tumorigenesis, and that de novo synthesized fatty acids are required for the rapid proliferation of cancer cells." (PMID 27564096, 2016). "Small molecule FASN inhibitors such as cerulenin, C75, and orlistat have been shown to induce apoptosis in several cancer cell lines and induce tumor growth delay." (PMID 27765901, 2016). "Transient knockdown of FASN suppressed hallmark structural and cytosolic/secretive proteins (vimentin, N-cadherin, fibronectin) in a model of EMT-induced cancer stem cells (CSC)." (PMID 27223424, 2016). "Reduction in FASN enzyme activity by chemical inhibitors including orlistat, cerulenin and triclosan have been reported to remarkably decrease progression in various cancer cell types." (PMID 27072583, 2016). "Upregulation of FASN expression in cancer has been shown to be consistent with metabolism of arachidonic acid by the COX pathway, a crucial player in inflammation and cancer progression." (PMID 27270654, 2016). "FASN catalyzes the synthesis of long chain fatty acids, promoting an altered lipogenic metabolism that is beneficial for cancer cell progression." (PMID 27246982, 2016). "Re-introducing BRG1 to BRG1- and BRM-depleted cancer cells increased FASN and ACC expression, increased de novo lipid synthesis, and partially restored cell proliferation." (PMID 27223259, 2016).
cancer (continued). "Increases in both FASN expression and activity are observed early in oncogenesis and correlate with cancer progression, with FASN-overexpressing tumors exhibiting more aggressive phenotypes." (PMID 27223259, 2016). "This acetate-mediated Ac-CoA production in conjunction with increased FASN is expected to promote LD synthesis in cancer cells." (PMID 27589734, 2016). "Histopathological analyses revealed that FASN knockdown shifted the differentiation pattern of cancer tissues from an aggressive, mesenchymal-like phenotype in CA1d tumors to a highly differentiated, epithelial-like phenotype in FASN-depleted CA1d lesions." (PMID 27223424, 2016). "Anti-FASN antibody showed that FASN was predominantly expressed in the cytoplasm of cancer epithelial cells." (PMID 26878389, 2016). "Substantial studies on fatty acid synthase (FASN) have focused on its role in regulating lipid metabolism and researchers have a great interest in treating cancer with dietary manipulation of amino acids." (PMID 27579768, 2016). "We treated cancer cells with gradient concentrations of acetate and found that FASN and ACACA mRNA expression were upregulated in a dose-dependent manner under hypoxia." (PMID 27357947, 2016). "ACC and FASN have been reported to be essential to cancer cell survival, and knocking down either ACC or FASN dramatically decreases cancer cell proliferation." (PMID 27223259, 2016). "Meanwhile, FASN has been proposed as a bona fide therapeutic target for cancers and many FASN inhibitors were developed as potential anticancer drugs." (PMID 27713175, 2016). "Human genomic FISH confirmed that FASN-overexpressing CA1d-derived tumors truly represented invasive human carcinomas, whereas the tumor tissues from FASN-depleted CA1d cells almost exclusively represented the normal duct-lobular system of the breast." (PMID 27223424, 2016). "FASN catalyzes the synthesis of palmitate providing substrates to affect multiple cellular functions and it has been proposed as a therapeutic target in cancer." (PMID 25855977, 2015). "FA synthesis by fatty acid synthase (FASN) is an anabolic process that is increased in many types of cancers, including that of the prostate." (PMID 26285134, 2015). "Another study showed that HER2 interacts with FASN and promotes FASN phosphorylation, which increases its activity and leads to cancer cell proliferation, and eventually, metastasis." (PMID 25751270, 2015). "Our data confirm plasma SAA1, PIGR, SPP24, FASN, and possibly THBS1 as potential biomarkers that are common to different types of malignant tumours and associated with Abnormal Savda." (PMID 25652121, 2015). "In normal tissues de novo fatty-acid synthesis is usually suppressed, and FASN expression is maintained at low levels whereas in cancer, the cells are highly dependent on the de novo synthesis." (PMID 26632252, 2015). "The effect of FASN in sustaining an elevated glycolytic activity of cancer cells can be explained by several mechanisms." (PMID 25970773, 2015). "The FASN was detected to be distributed in the cell cytoplasm and was significantly correlated with cancer grade (p = 0.000) and FIGO staging (p = 0.000)." (PMID 25433947, 2015). "Cancer cells prefer to derive their need for fatty acid via de novo lipogenesis in comparison to normal human tissues which prefers to utilize exogenous lipids, as a consequence of which cancer cells harbor high levels of FASN and ACACA." (PMID 26632252, 2015). "Using immunohistochemical (IHC) analysis, expression of FASN, pAMPK and p62 was assessed in clinical samples, which included matched primary cancer, liver metastases and normal colonic mucosa from 19 CRC patients." (PMID 25970773, 2015). "Using immunofluorescence, we further confirmed that the expression of FASN in three cancer cell lines was markedly suppressed by GA intervention." (PMID 25895130, 2015).
cancer (continued). "Collectively, these results suggest that, under stress conditions, overexpression of FASN protects cancer cells by dampening signaling triggered by energy stress." (PMID 25970773, 2015). "Animal studies of triclosan exposure and cancer development have included long-term studies of its carcinogenicity and short-term studies examining fatty acid synthase-related cancer growth inhibition." (PMID 24566048, 2014). "The abundant expression of FASN and its function on de novo fatty acid synthesis in cancer cells is accompanied by carcinogenesis and is relevance to unsatisfactory prognosis." (PMID 25255125, 2014). "Inhibition of FASN has emerged as a promising therapeutic target in cancer, and numerous inhibitors have been investigated." (PMID 25313139, 2014). "In conclusion, this study provides evidence that high levels of FASN expression in cancer cells are crucial for cell proliferation and survival as well as for sensitivity to capsaicin or other FASN inhibitors." (PMID 25255125, 2014). "In conclusion, increased PEMT expression in NSCLC tissues (relative to the adjacent non-cancer lung tissue) predicts shorter patient survival, independently of increased FASN or LPL activities in the same cancer tissues." (PMID 24932311, 2014). "In the present study, it was found that quercetin not only exerted a high inhibitory effect on intracellular FASN, but also influenced the normal life cycle of cancer cells." (PMID 25009654, 2014). "Several studies have reported that pharmacologic inhibition of FASN expression and its enzymatic activity can induce apoptosis in cancer cell." (PMID 25255125, 2014). "Collectively, our results provide novel evidence that capsaicin exhibits a potent anti-cancer property by targeting FASN protein in HepG2 cells." (PMID 25255125, 2014). "The phosphorylation (i.e. activation) of Akt was shown to induce the expression of FASN and to trigger aggressive malignancy in cancer cells." (PMID 24960186, 2014). "Although there are several novel FASN inhibitors, cerulenin and C75 are the most utilized FASN inhibitors, and they exhibit potent anti-tumor activity in cancer cells." (PMID 24866893, 2014). "RNAi knockdown experiments have shown that multiple cancer cell lines depend on FASN for proliferation and survival." (PMID 25009654, 2014). "Although FASN inhibitors showed promising anti-cancer activities, their evaluation in clinical trials was challenged due to pharmacological limitations." (PMID 25313139, 2014). "Overexpression of FASN in cancer cells suggests that tumors require higher levels of fatty acids than can be acquired from the circulation, but also indicates higher levels of endogenous production." (PMID 25009654, 2014). "This study investigated the inhibitory effect of quercetin on human liver HepG2 cancer cells with overexpression of FASN." (PMID 25009654, 2014). "While many studies have focused on the FASN enzyme in cancer biology, few studies have addressed the roles of proteins that modify FASN activity, such as S14." (PMID 25472762, 2014). "In summary, these results demonstrated that the hydroxyl group is critical for the activity of TCS in inhibiting cancer cell growth and reducing cellular lipid levels and FASN expression." (PMID 25313139, 2014). "Such an over-expression of FASN observed in cancer cells is, therefore, considered the important biological role of this enzyme in tumorigenesis." (PMID 25255125, 2014). "This suggests that the de novo synthesis of LCFAs by inhibition of FASN in cancer cells becomes a focus for the selective target of anti-cancer therapeutics." (PMID 25255125, 2014).